MMP13 (matrix metallopeptidase 13)
Diseases named in the same sentence as MMP13 in open-access papers (continued):
Sharing a sentence is not in itself a finding about the gene and the disease.
cervical cancer (5 papers, 2017 to 2025). A primary or metastatic malignant neoplasm involving the cervix. "IL‐6 was used to activate STAT3 signaling pathway in HeLa and SiHa cells, and the expression of N‐cadherin, E‐cadherin, vimentin, MMP‐3, and MMP‐13 were examined to confirm the activation of the STAT3 signaling pathway to promote the invasion potential of cervical cancer cells." (PMID 33040485, 2020). "HeLa and SiHa cells were treated with RES and S3I201 or AG490, and the expression levels of N‐cadherin, E‐cadherin, vimentin, MMP‐3, and MMP‐13 were examined to confirm that the role of STAT3 phosphorylation was inhibited by RES on the invasion potential of cervical cancer cells." (PMID 33040485, 2020). "Notably, higher levels of MMP13 were observed in cervical cancer tissues compared to adjacent noncancerous tissues, with these elevated levels correlating with a poorer prognosis for cervical cancer patients." (PMID 40168262, 2025). "Thus, it seems that part of the beneficial effects of calcitriol on cervical cancer may be attributed to its suppression of MMP7 and MMP-13 gene expression." (PMID 40168262, 2025). "The protein levels of p‐STAT3 (Tyr705), N‐cadherin, E‐cadherin, vimentin, MMP‐13, and MMP‐3 in the tumor tissues grown from HeLa cells were determined through IHC and Western blot to examine the effects of RES on STAT3 phosphorylation, EMT, and cervical cancer cell invasion." (PMID 33040485, 2020).
Cirrhosis (5 papers, 2015 to 2026). A chronic disorder of the liver in which liver tissue becomes scarred and is partially replaced by regenerative nodules and fibrotic tissue resulting in loss of liver function. "After erlotinib treatment, expression of antifibrotic pathways, including Mmp2, Mmp3, and Mmp8, were enhanced in PCLS from CDAHFD-induced cirrhosis, while expression of profibrotic pathways, including Mmp9 and Mmp13, were hampered." (PMID 39445861, 2024). "On the other hand, compared to the cirrhosis and placebo groups, the animals treated with doxazosin and carvedilol showed a 2-fold greater expression of MMP-13 and a lower expression of TIMP-2 (p<0.05), both of which reached levels similar to the intact group." (PMID 30643808, 2018). "The expression of TIMP-2 decreased and that of MMP-13 increases in animals treated with adrenoblockers with respect to the group with cirrhosis." (PMID 30643808, 2018). "After 20 weeks of treatment with CCl4, the hamsters of the cirrhosis group displayed alterations in the expression of genes responsible for regulating the degradation of the extracellular matrix, such as MMP-13 and TIMP-2." (PMID 30643808, 2018). "Compared to the intact group, the group with cirrhosis exhibited a decrease in the level of MMP-13 and a 3-fold increase in the level of TIMP-2." (PMID 30643808, 2018). "In the cirrhosis group, the level of MMP-13 decreased and that of TIMP-2 increased, thus inhibiting MMP activity." (PMID 30643808, 2018). "To determine whether changes in MMP13 levels were relevant to the human progression of NAFLD, we evaluated the MMP13 protein levels by western analysis from liver lysates of normal livers and compared them to livers with steatosis, steatohepatitis or NAFLD related cirrhosis." (PMID 25880591, 2015).
dental caries (5 papers, 2018 to 2025). The decay of a tooth, in which it becomes softened, discolored, and/or porous. "When the influence of the MMP13-77 A/G polymorphism and oral hygiene practices on dental caries experience was analyzed by binary logistic regression, only the presence of dentobacterial plaque showed a significant association." (PMID 40863105, 2025). "Additionally, mutant alleles of MMP13 have been associated with a risk of dental caries, even after controlling for candidate genes, dentition type, and nutritional factors." (PMID 39723289, 2024). "The aim of the study was to analyse Czech children with primary/permanent dentition polymorphisms in those genes encoding MMP2, MMP3, MMP9, MMP13, MMP16, and MMP20, which had been previously associated with dental caries in other populations." (PMID 32398053, 2020). "Single nucleotide polymorphisms (SNPs) in MMP2 (rs243865), MMP9 (rs17576), MMP13 (rs2252070), and TIMP2 (rs7501477) were investigated for their association with caries in 505 subjects, 212 caries-free subjects and 293 subjects presenting with dental caries." (PMID 32116745, 2020). "Allele frequencies for MMP2, MMP13 and TIMP2 polymorphisms were significantly different between individuals with or without dental caries." (PMID 32116745, 2020).
esophageal cancer (5 papers, 2010 to 2024). A primary or metastatic malignant neoplasm involving the esophagus. "After measuring MMP13 gene expression in sixty-six pairs of esophageal cancer and normal tissues, we observed that the rs2252070 A protective allele carriers showed decreased oncogene MMP13 expression." (PMID 27245877, 2016). "Increased expression of MMP13 in oesophageal cancer is related to cancer aggressiveness." (PMID 25609201, 2015). "MMP13 or (Collagenase-3) and MGAT5 play known roles in tumor metastasis and invasion in gastrointestinal tract tumors, head and neck squamous carcinomas esophageal cancer and colorectal tumors." (PMID 37256183, 2023).
Granuloma (5 papers, 2014 to 2025). A compact, organized collection of mature mononuclear phagocytes, which may be but is not necessarily accompanied by accessory features such as necrosis. "In contrast with these results, we did not observe a significant decrease in M1 marker genes, including MMP9, NOS2, CCL2, IL-6 and ARG2, in granuloma FCMs compared with NFMs, although MMP13 and NF-κB1 levels, which are also M1-related genes, were decreased." (PMID 26197235, 2015). "Furthermore, we identified Flrt2, Hyal1, and Mmp13 as novel molecular markers of Plin2-expressing macrophages, which were localized to the peripheral rim regions of necrotizing granulomas." (PMID 40843005, 2025). "Clearly, the absence of T and B lymphocytes had little impact on extent of MMP-13 or MMP-14 staining, consistent with the PCR data obtained from granuloma FCMs." (PMID 25389425, 2014).
head and neck cancer (5 papers, 2014 to 2024). A primary or metastatic malignant neoplasm affecting the head and neck. "Based on this study, we have first documented that epiberberine inhibits metastasis by targeting MMP‐13 in head and neck cancer cells." (PMID 37710409, 2023). "Higher MMP-13 expression correlates closely with a higher number of blood vessels in human head and neck cancer." (PMID 35805035, 2022). "Aggressive cancers have been shown to express higher levels of MMP-13 than less aggressive ones in prostate, breast and head and neck cancers (HNSCC)." (PMID 35805035, 2022). "Additionally, IFITM1 has also been shown to enhance migration and invasion in head and neck cancer cells through activation of matrix metalloproteinase 12 (MMP12) and MMP13, key enzymes involved in the degradation of the basement membrane that allows cells to infiltrate into adjacent tissues." (PMID 26897526, 2016).
psoriasis (5 papers, 2019 to 2025). An autoimmune condition characterized by red, well-delineated plaques with silvery scales that are usually on the extensor surfaces and scalp. "In IMQ-induced psoriasis mouse model, intravenous infusion of hUC-MSCs downregulated the expression of matrix metalloproteinase-13 (MMP13) in skin lesions." (PMID 40748586, 2025). "In summary, MMP13 expression is increased in skin lesions and serum samples of patients with psoriasis." (PMID 34172768, 2021). "Intriguingly, our data indicate that tazarotene treatment and NB-UVB irradiation inhibits MMP13 expression, which is accompanied by improvement in the psoriasis-like phenotype." (PMID 34172768, 2021). "In this study, we determined the expression of MMP13 in patients with psoriasis and investigated the influence of tazarotene/acitretin and NB-UVB irradiation on the expression of MMP13 in imiquimod (IMQ)-induced mice and HaCaT cells." (PMID 34172768, 2021). "Based on these from HaCaT keratinocytes cells and animal experiments, we suggest that tazarotene/acitretin and NB-UVB irradiation can inhibit the expression of MMP13 in HaCaT keratinocytes and psoriasis mouse models." (PMID 34172768, 2021). "Retinoid and NB-UVB exert their synergistic beneficial effects on psoriasis likely through regulation of MMP13 expression and secretion." (PMID 34172768, 2021). "We showed that patients with psoriasis had increased levels of MMP13 protein in skin lesions and serum samples." (PMID 34172768, 2021). "In this study, we showed that the levels of MMP13 in skin lesions and serum samples of patients with psoriasis were higher than those in the control group." (PMID 34172768, 2021). "Consistently, tazarotene treatment or NB-UVB irradiation attenuated imiquimod-induced psoriasis-like dermatitis and decreased MMP13 expression in a mouse model." (PMID 34172768, 2021). "The effects of tazarotene/acitretin and NB-UVB on MMP13 expression were also investigated in a mouse model of psoriasis." (PMID 34172768, 2021). "MMP13 staining was strongly positive in each layer of skin tissues in patients with psoriasis." (PMID 34172768, 2021). "The expression of MMP13 was analyzed in patients with psoriasis." (PMID 34172768, 2021). "Since MMP13 can modulate keratinocyte migration and inflammatory response in murine skin wound models, we hypothesized that MMP13 might play an important role in the pathogenesis of psoriasis." (PMID 34172768, 2021). "The changes of cells to cells and cells-matrix adhesion in the epidermis of psoriasis may be related to the abnormal increase of MMP13." (PMID 34172768, 2021). "High expression of MMP13 in psoriasis skin lesions may lead to changes in the microenvironment of keratinocytes and epidermal dynamics, consequently affecting the proliferation and differentiation of keratinocytes." (PMID 34172768, 2021). "Second, there is no direct evidence supporting that reduction of MMP13 expression is a causal factor for the improvement of psoriasis-like phenotype by tazarotene and NB-UVB." (PMID 34172768, 2021). "Similarly, tazarotene and NB-UVB irradiation led to synergistic inhibition of MMP13 expression in an IMQ-induced psoriasis-like mouse model." (PMID 34172768, 2021). "However, their impact on MMP13 expression in the context of psoriasis has yet to be determined." (PMID 34172768, 2021). "Blockade of MMP13 activity may have therapeutic potential in improving symptoms of psoriasis." (PMID 34172768, 2021). "Therefore, MMP13 may be a potential therapeutic target for psoriasis." (PMID 34172768, 2021). "We found that MMP2, MMP12, MMP13, TIMP2, and TIMP4 distinguished psoriasis from psoriatic arthritis patients undergoing a systemic treatment, with a good diagnostic accuracy (Area under the ROC Curve (AUC) > 0.7)." (PMID 31717649, 2019).
psoriasis (continued). "A set of biomarkers, composed matrix metalloproteinases, and their tissue inhibitors comprises MMP2, MMP12, MMP13, TIMP2, and TIMP4 whose circulating levels are higher psoriasis undergoing systemic therapy compared to the parallel with psoriatic arthritis cohort." (PMID 34715781, 2021).
sarcoma (5 papers, 2019 to 2025). A usually aggressive malignant neoplasm of the soft tissue or bone. "Studies have shown that WNT7B, CA9, MMP13, and RAC3 are associated with poor outcomes in sarcomas." (PMID 36428766, 2022). "Another study identified the up-regulation of MMP13 and WNT7B (which influence oncogenesis) in undifferentiated pleomorphic sarcomas, their presence suggesting the poor differentiation of this subtype." (PMID 40981124, 2025).
skin carcinoma (5 papers, 2012 to 2022). "Immunoexpression of MMP-13 has been associated with malignant transformation in skin cancer, where it degrades the extracellular matrix (ECM)." (PMID 36505148, 2022). "In addition, MMP-13 contributes to experimental choroidal neovascularization and acts as a stromal mediator in controlling persistent angiogenesis in skin carcinoma." (PMID 28068383, 2017). "MMP-13 acts as a stromal mediator in controlling persistent angiogenesis in skin carcinoma." (PMID 28068383, 2017). "Moreover, in HNSCCs, urinary tract or skin carcinomas, MMP-13 expression is observed not only in tumor cells but also in stromal cells surrounding the tumor, in particular those located at the invading front." (PMID 26193700, 2015). "Notably a recent study highlighted bone-marrow derived myofibroblasts found at the primary tumour site in a skin cancer model as the principal source of MMP-13 in situ, and that this MMP was required for subsequent invasive behaviour." (PMID 25596732, 2015).
cutaneous melanoma (4 papers, 2010 to 2023). A primary melanoma arising from atypical melanocytes in the skin. "The signature genes CEACAM5, ITGA10 and MMP13 had the highest proportion of mutations among all 467 patients with cutaneous melanoma of the skin." (PMID 34675134, 2021). "In general, the expression of MMP2, MMP13, MMP16, MMP17 and MMP25 were significantly associated with skin cutaneous melanoma (SKCM) patients prognosis, among which MMP2 low expression benefited patients the most." (PMID 36788565, 2023). "Interestingly, protein expression of MMP13 is absent from nevi, but was noted in almost 50% of cutaneous melanoma." (PMID 20667128, 2010).
glaucoma (4 papers, 2013 to 2023). Increased pressure in the eyeball due to obstruction of the outflow of aqueous humor. "Here we showed that MMP-7 (a matrilysin) and MMP-13 (also known as collagenase-3) are the most important MMPs in glaucoma." (PMID 36973823, 2023). "The up-regulation of several MMPs specifically MMP-2, MMP-9, and MMP-13 are reported in steroid induced mice model of glaucoma." (PMID 25988186, 2015). "In another study, mRNA expression of MMP-1 (but not MMP-2, MMP-9, and MMP-13) was found to be significantly up-regulated in steroid induced sheep model of glaucoma." (PMID 25988186, 2015).
keloid (4 papers, 2011 to 2024). An irregularly shaped, elevated mark on the skin caused by deposits of excessive amounts of collagen during wound healing. "Analogously, acoustic shock waves applied in multiple sessions permitted the reduction in the number of keloids’ collagen fibres, thanks to the increase in the matrix metalloproteinase MMP13 gene expression." (PMID 39681689, 2024). "Specifically, MMP-2 and MMP-13 contribute extensively to break down types I and III collagens, the most abundant types of collagen in keloids and hypertrophic scars." (PMID 27339758, 2016). "Recently clinical studies have shown that use of a 585 nm flashlamp-pumped pulsed-dye laser resulted in the regression or arrest of keloid development by reducing the expression of TGF-β1in keloid tissues and increasing the expression of matrix metalloproteinase (MMP)-13 (also called collagenase-3)." (PMID 21923916, 2011).
liver cancer (4 papers, 2013 to 2025). An epithelial or non-epithelial malignant neoplasm that arises from the liver. "Upregulation of MMP13 was linked to lymph node metastasis in HCC, suggesting that MMP13 likely regulates liver cancer metastasis." (PMID 23762330, 2013). "MMP2, MMP9 and MMP13 proteins play significant roles in liver cancer invasion and migration." (PMID 39744479, 2025).
liver cirrhosis (4 papers, 2011 to 2025). "Our data correlate HF activation of the Atf4/ISR with changes in the transcription of multiple genes, including ECM regulators such as Mmp13 which was previously linked to HF anti-fibrotic effects on fibrotic potential in a liver cirrhosis model." (PMID 21974968, 2011). "This possibility is supported by our previous work on NIL-cirrhotic hamsters, in which both overexpression of MMP-13 and decreased expression level of TIMP-2 were accompanied by a significant regression in liver cirrhosis." (PMID 34926704, 2021).
metastatic melanoma (4 papers, 2015 to 2025). A melanoma that has spread from its primary site to another anatomic site. "Moreover they suggest that other MMPs (MMP7, MMP10, MMP11, and MMP13) might be implicated in CNS invasion by metastatic melanoma cells." (PMID 25692137, 2015). "MMP-13 expression is also reported in primary and metastatic melanomas and has been shown to enhance the invasion capacity of HT1080 fibrosarcoma cells." (PMID 31139331, 2019). "Moreover, ArcA significantly inhibited cell migration and invasion in metastatic melanoma cell lines, accompanied by reduced expression levels of p-GSK-3β (Ser9), MMP-9, and MMP-13, suggesting that its anti-metastatic effects may be partially mediated through GSK-3β, MMP-9, and MMP-13." (PMID 39948552, 2025).
Alzheimer disease (3 papers, 2021 to 2024). A progressive, neurodegenerative disease characterized by loss of function and death of nerve cells in several areas of the brain leading to loss of cognitive function such as memory and language. "It is important to determine whether lactobacillus inhibits senescence by decreasing DNMT1, m1A, m6A, TDP-43, GADD45, MMP-13, and ADAMTS1, and increasing TET2, 3MST, H2S and TIMPs in RED and Alzheimer’s disease." (PMID 39456478, 2024). "Note that the Alzheimer disease-presenilin pathway identified as the most enriched by the Panther algorithm is related to ECM remodeling (genes included in the pathway: Mmp9, Mmp8, Mmp2, Mmp13, Mmp12)." (PMID 35386010, 2022).
bone cancer (3 papers, 2012 to 2022). A primary or metastatic malignant neoplasm affecting the bone or articular cartilage. "Our current studies indicate that Osx controls MMP13 expression in osteoblasts, suggesting a possible involvement of Osx in bone cancer in addition to normal bone development." (PMID 23185634, 2012). "Subtoxic doses of eIF2α phosphatase GADD34/PP1c inhibitors guanabenz or salubrinal reduce breast and bone cancer cell migration/invasion through the reduction of SRC and RAC1 activity and through the modulation of MMP13 expression (for salubrinal)." (PMID 31064137, 2019).
cartilage disease (3 papers, 2021 to 2025). Softening and degeneration of the CARTILAGE. "Increased expression of MMP13 signifies the active cartilage diseases and precedes cartilage degeneration and ALN treatment has been shown to reduce the MMP13 expression in knee articular cartilage." (PMID 39004686, 2024).
colorectal adenoma (3 papers, 2016 to 2021). An adenoma that arises from the colon or rectum. "Our aim was to determine whether MMP-13 expression in colorectal adenomas and carcinomas is useful for a concise and accurate diagnosis." (PMID 27716617, 2016). "Here we investigate the association between grade of dysplasia and Matrix metalloproteinase-13 (MMP-13) expression in 137 biopsies from patients with cancerous and non-cancerous colorectal adenomas." (PMID 27716617, 2016). "Thus, MMP-13 IRS could also be helpful to predict metastatic behaviour, prognosis, and relapse at an early stage of cancerous and precancerous colorectal adenoma, which is definitely not accessible by conventional histology." (PMID 27716617, 2016).
cutaneous squamous cell carcinoma (3 papers, 2020 to 2022). "Activation of EPHB2 promotes the progression of cutaneous squamous cell carcinoma cells by accelerating the production of invasive proteinases like MMP13 and MMP1." (PMID 32102656, 2020).
dysplasia (3 papers, 2009 to 2023). A usually neoplastic transformation of the cell, associated with altered architectural tissue patterns. "In that study, Bo and colleagues observed continuous loss of sGAG and significantly increased expression of type X collagen and MMP-13, two markers of cartilage degeneration, in dysplasia hip as compared to controls." (PMID 25294293, 2014). "Expression of MMP13 is very restricted in normal tissues and is not found in skin keratinocytes, except under conditions of wound healing, dysplasia or neoplasia." (PMID 19142229, 2009).